CRYGS (crystallin gamma S)
Description:
Crystallins are the dominant structural components of the vertebrate eye lens.
Synonyms: CRYG8; CTRCT20
Tractability: No criterion of Open Targets' tractability assessment is met for any kind of drug.
Gene: Protein-coding gene on chromosome 3 (186,538,441 to 186,546,702, reverse strand). Ensembl gene ENSG00000213139.
Subcellular location (Human Protein Atlas): Cytosol
Gene Ontology:
Molecular function: protein binding; structural constituent of eye lens
Biological process: lens development in camera-type eye; visual perception
Genetic constraint (gnomAD): Loss-of-function variants: 11 observed, 20.68 expected, observed/expected ratio (o/e) 0.53, 90% interval 0.33 to 0.88. The upper end of that interval is the gene's LOEUF score, 0.88, which puts it in group 3 of 6, group 1 being the genes least tolerant of losing a copy. Missense variants: 198 observed, 233.99 expected, observed/expected ratio (o/e) 0.85, 90% interval 0.75 to 0.95. Synonymous variants: 65 observed, 77.84 expected, observed/expected ratio (o/e) 0.84, 90% interval 0.68 to 1.03.
Homologues: Orthologues: chimpanzee CRYGS (99% identical), macaque CRYGS (99% identical), guinea pig CRYGS (94% identical), dog CRYGS (93% identical), pig CRYGS (91% identical), rabbit CRYGS (90% identical), mouse Crygs (90% identical), rat Crygs (90% identical), zebrafish crygs1 (69% identical), zebrafish crygs2 (65% identical). Paralogues in human: CRYGB (53% identical), CRYGC (52% identical), CRYGA (50% identical), CRYGD (49% identical), CRYBB1 (37% identical), CRYBA1 (35% identical), CRYBB3 (34% identical), CRYBB2 (34% identical), CRYBA4 (33% identical), CRYBA2 (32% identical), CRYBG1 (31% identical), CRYGN (29% identical), and 2 more.
Diseases named in the same sentence as CRYGS in open-access papers:
CRYGS is named in the same sentence as 5 diseases in open-access papers, as found by Europe PMC text mining. Sharing a sentence is not in itself a finding about the gene and the disease. The quoted sentences say what the papers report.
Coats disease (1 paper, 2016). Coats disease (CD) is an idiopathic disorder characterized by retinal telangiectasia with deposition of intraretinal or subretinal exudates, potentially leading to retinal detachment and unilateral blindness. "Of the identified DCPs, several crystalline-related proteins, including CRYBB1, CRYBB2, CRYGS and CRYGD, were down-regulated in the AH from patients with Coats' disease." (PMID 27416065, 2016).
lamellar cataracts (1 paper, 2025). "Gene mutations of CRYGS, an essential protein for lens transparency, also cause congenital lamellar cataracts in humans." (PMID 40649110, 2025).
CRYGS also shares sentences with these, for which no sentence is quoted: diabetes (1 paper); ocular hypertension (1); Parkinson disease (1).